MEN1 (menin 1)
Diseases named in the same sentence as MEN1 in open-access papers (continued):
Sharing a sentence is not in itself a finding about the gene and the disease.
gastrinomas (continued). "This case elucidates not only the difficulty of gastrinoma localization in medically refractory ZES but also reinforces the need to screen patients with MEN1 presenting with acute abdominal pain and dyspepsia for ZES." (PMID 35919366, 2022). "The most common functional pancreatic NET in MEN1 is a gastrinoma, which can also occur in the duodenal mucosa as small multifocal tumors and leads to the Zollinger-Ellison Syndrome (ZES)." (PMID 33716975, 2021). "F-panNENs related with MEN1 are mostly represented by gastrinomas (10–54% of patients with gastrinoma)." (PMID 34885063, 2021). "MEN1 gastrinomas are prevalently located within the duodenum (over 90% of gastrinomas), and less than 10% of cases affect the pancreas." (PMID 33919851, 2021). "Although most gastrinomas sporadically arise, they are the most common functioning PNENs in patients with MEN1 (20–25% of all gastrinomas occur in these patients)." (PMID 33672085, 2021). "Duodenal gastrinomas are usually < 1 cm in diameter and are often multicentric, especially in patients with MEN1." (PMID 33672085, 2021). "According to current MEN1 guidelines, patients with gastrinoma or multiple pancreatic NET at any age should be tested for MEN1 and therefore screened for HPT." (PMID 32276412, 2020). "Disturbance of bone metabolism and vitamin D alteration in patients with GEP–NET and MEN1 are mainly related to the coexistence of HPT, but the association of gastrinoma and ZES seem to worsen HPT." (PMID 32276412, 2020). "Surgical treatment of gastrinomas/ZES in patients with MEN1 is controversial given the multiplicity and small size of these tumors, that leads to rare surgical cure without aggressive resections." (PMID 31263451, 2019). "Gastrinomas in patients with MEN1 lead to a decreased life expectancy with 5 and 10‐year OS rates of 83% and 65%, respectively." (PMID 31401809, 2019). "In conclusion, life expectancy in patients with MEN1 having gastrinomas is reduced compared with other studies." (PMID 31401809, 2019). "This population‐based cohort study assessed prognostic factors of survival in patients with MEN1‐related gastrinomas." (PMID 31401809, 2019). "Patients with MEN1 having gastrinomas were identified in the Dutch MEN1 database from 1990 to 2014 based on fasting serum gastrin (FSG) levels and/or pathology." (PMID 31401809, 2019). "Gastrinomas in MEN1 are typically diagnosed by the age of 40 (on average 10 years earlier than sporadic gastrinomas) and are most commonly microadenomas that occur primarily in the duodenum (>80%), and less frequently in the pancreas." (PMID 31263451, 2019). "Gastrinomas are the most common (over 50% of cases) MEN1 secreting GEP-NETs; about 90% are located in the duodenum and 10% in the pancreas." (PMID 30428914, 2018). "In patients with MEN1 and gastrinoma, almost all gastrinomas arise in the duodenum and are sometimes accompanied by pancreatic gastrinomas." (PMID 29181825, 2017). "This case of MEN1 with pancreaticoduodenal gastrinomas, accompanied with a high level of serum gastrin (≥3000 pg/mL, normal: ≤200 pg/mL), developed severe esophageal stenosis and complained of dysphagia, despite administration of full-dose PPI." (PMID 28270118, 2017). "Duodenal gastrinomas occur in approximately 40% of patients with MEN1 and about 25% of all patients with gastrinoma have MEN1." (PMID 28965289, 2017). "Gastrinomas are the first presentation of MEN1 in 29–40% of patients; in most cases the patient will already have developed hyperparathyroidism which has not yet been diagnosed." (PMID 28965289, 2017). "The majority of patients with MEN1 will develop primary hyperparathyroidism by age 50 and thus MEN1 should always be suspected in patients with gastrinoma and a personal or family history of hypercalcaemia or nephrolithiasis." (PMID 28965289, 2017).
gastrinomas (continued). "PD, along with regional lymphadenectomy, appears to be the treatment of choice for radical treatment of MEN1 gastrinoma given the almost exclusive presence of gastrinoma in the duodenum." (PMID 24213321, 2012). "Compared to the sporadic counterpart MEN1, gastrinomas are more prevalently located in the duodenum (80%–100% of cases) than in the pancreas." (PMID 24213321, 2012). "In addition, the distribution of the tumor grades in patients with gastrinomas with MEN1/ZES differed from those with sporadic ZES in having more patients with lower grades (G1: 83% vs. 39%; G2 (11% vs. 54%) G3: (5.6% vs. 6.1%)." (PMID 41463062, 2025). "Diagnosing gastrinomas in MEN1 may be challenging with early detection through screening leading to milder phenotypes and widespread PPI use and risk of cessation make obtaining gastric pH off PPI difficult." (PMID 39587981, 2025). "This increased proportion of patients with gastrinomas having aggressive behavior with higher grades of the primary gastrinoma in sporadic ZES patients correlates with results from prospective NIH clinical studies of patients with either sporadic ZES or ZES with MEN1." (PMID 41463062, 2025). "Early detection of these lesions may have a role in the diagnosis of MEN1 in the context of a MEN1-related primary manifestation (sensitivity 75%, specificity 95% in the presence of gastrinomas)." (PMID 39946193, 2025). "Class Ib NETs can include functioning gastrinoma lesions that are sporadic or associated with MEN1, or non-functioning somatostatin-producing NETs or non-functioning serotonin-producing tumors." (PMID 39941746, 2025). "Considering that patients with MEN1 may have gastrinoma, gastrin levels were measured and found to be 27.30 pg/mL (normal range:13.0-115.0 pg/mL), so a diagnosis of gastrinoma was not supported." (PMID 40421248, 2025). "For small PNETs associated with MEN1, including nonfunctional and gastrinomas, observation in these patients has recommended by several PNET societies." (PMID 37046665, 2023). "While small tumors in the setting of MEN1 might be observed, sporadic gastrinomas should undergo surgical exploration, unless there is a medical contraindication to surgery." (PMID 37046665, 2023). "It is estimated that 25% of gastrinomas occur in patients with MEN1." (PMID 37623030, 2023). "Considering the young average age of diagnosis of MEN1–ZES (around 40 years), one might argue that an overall survival of 15–20 years results in a substantial number of patients with MEN1 and gastrinomas dying before the age of 60." (PMID 36473964, 2023). "Therefore, in patients with MEN1, screening for gastrinomas should focus on the proximal part of the duodenum, and sampling of other tissues, especially the pancreas, is not required." (PMID 37867522, 2023). "What kind of surgery has been performed for gastrinomas in patients with MEN1?" (PMID 36473964, 2023). "Moreover, the management of MEN1 gastrinomas greater than 1 cm in size is advised to be surgical, preferably pancreaticoduodenectomy, to avoid liver metastases and achieve a better prognosis." (PMID 37568540, 2023). "Curative surgery should be recommended for gastrinomas in patients with MEN1." (PMID 36473964, 2023). "However, a study of MEN1-gastrinomas showed that LOH at the 11q13 locus occurred in only 46% of cases, with either partial, complete, or no LOH observed in small synchronous tumors from the same patient." (PMID 37492626, 2023). "Beside thymic carcinoid, gastrinomas and non-functioning dpNEN are the leading causes of disease-related death in MEN1 patients." (PMID 35454834, 2022). "Moreover, because approximately 25% of MEN1 patients die from cancer due to malignant gastrinomas, an examination of the gastroduodenum is necessary." (PMID 35255927, 2022).
gastrinomas (continued). "Therefore, no recommendation exists concerning the surgical treatment of MEN1-related gastrinoma, and potential benefits of surgical indication should be weighted with the risk of an aggressive surgery and potential reoperations." (PMID 34885063, 2021). "The surgical indication for MEN1-related gastrinoma is a controversial issue." (PMID 34885063, 2021). "However, almost all of these gastrinomas occurs in the duodenum, pancreatic gastrinoma in the setting of MEN1 being very rare." (PMID 34885063, 2021). "On the other hand, reports suggest that aggressive surgery could be beneficial for duodenal/pancreatic gastrinoma in the context of MEN1, even in the case of locally advanced disease." (PMID 34885063, 2021). "Furthermore, MEN1-related gastrinomas are believed to be highly responsive to somatostatin analogue therapies." (PMID 34885063, 2021). "In this regard, it is correct to point out that patients with symptomatic MEN1 gastrinomas, a long-time treatment by H2-blockers or PPIs, may stimulate gastric neuroendocrine cells proliferation contributing to the clinical outcome and severity of GEP-NETs." (PMID 33312161, 2020). "Nearly one third of these gastrinomas are found in patients with MEN1 genetic syndrome." (PMID 30657883, 2019). "In addition, the understanding that MEN1 gastrinomas mostly originate in the duodenum instead of the formerly assumed pancreatic origin, emphasizes the need for new studies." (PMID 31401809, 2019). "The observed prognostic factors might aid clinicians in selecting patients with MEN1 having gastrinomas for more intensive follow‐up regimens or extended localization imaging." (PMID 31401809, 2019). "This study is limited by the challenges of gastrinoma diagnosis in patients with MEN1." (PMID 31401809, 2019). "OS rates of patients with MEN1 gastrinoma after 5 and 10 years were 83% and 65%, respectively." (PMID 31401809, 2019). "Life expectancy of patients with MEN1 gastrinoma is reduced." (PMID 31401809, 2019). "LM in both MEN syndromes may originated from various endocrine tumors, for instance from gastrinoma or thymic carcinoid in MEN1 or primarily from medullary thyroid carcinoma in MEN2-syndrome." (PMID 30817772, 2019). "Initial FSG levels determined prognosis in patients with MEN1 gastrinoma." (PMID 31401809, 2019). "Sixty‐three patients with gastrinoma (16% of the MEN1 population) were identified." (PMID 31401809, 2019). "The occurrence of germline MEN1 mutations in all patients with sporadic, non-familial parathyroid adenomas is 1%, in gastrinomas is 5%, in prolactinoma is 1%, and in foregut carcinoids is 2%." (PMID 23933118, 2014). "Studies of MEN1-related mortality have demonstrated that 28–46% of deaths are directly related to MEN1, most commonly as a result of malignant pancreatic islet tumors, gastrinomas and foregut carcinoids." (PMID 23933118, 2014). "The incidence of MEN1 has been estimated from randomly chosen postmortem studies to be 0.25% and to be 1–18% among patients with primary hyperparathyroidism, 16–38% among patients with gastrinomas, and less than 3% among patients with pituitary tumors." (PMID 23933118, 2014). "ZES affects at least 40% of MEN1 patients, representing 20% of all diagnosed gastrinomas." (PMID 24213321, 2012). "In a prospective follow-up (mean eight years) of 57 MEN1 gastrinoma patients, gastric carcinoids were reported in about 25% of the cases, being more frequently represented in patients affected by aggressive gastrinoma (about 60%) than in those with non aggressive gastrinoma (only 10%)." (PMID 24213321, 2012). "In MEN1, duodenal gastrinomas are usually multiple, smaller than 5 mm in diameter, associated to foci of gastrin-positive cells, and with a predominance in the proximal duodenum, while the pancreatic counterpart is usually single and greater than 1 cm in diameter." (PMID 24213321, 2012).
gastrinomas (continued). "Furthermore, in the case of ZES/MEN1 patients, the controversial role of surgery or the type of surgery in these patients for the gastrinomas or NF-pNET will complicate the design of any study to address the other controversial issues in these patients discussed here." (PMID 41463062, 2025). "Indeed, while PPI treatment is very efficient to downregulate gastrin hypersecretion, MEN1 related gastrinomas are usually multiple and located in the duodenum, hence, it is unlikely to achieve curative resection using conservative pancreatic surgery (such as enucleation]." (PMID 32947997, 2020). "There is a high prevalence of urolithiasis and early bone mineral loss in young individuals with MEN1-associated PHPT, and bone or renal complications are progressively more frequent, extensive, and severe in long-standing PHPT cases and in those associated with gastrinoma." (PMID 31263451, 2019). "Furthermore, in 31–58% of patients with sporadic gastrinomas without a germline MEN1 mutation present, there is an MEN1 gene mutation in the gastrinomas, which is a similar situation in other sporadic non-gastrinoma pNETS which can have MEN1 mutation only in the pNET in 20–40%." (PMID 41463062, 2025). "In MEN1/ZES patients, duodenal gastrinomas have been shown to arise from the duodenal G cells by a process of progressive hyperplasia in a similar manner to that proposed for the response of ECL cells to gastrin in the stomach." (PMID 41463062, 2025). "Patients developing multiple parathyroid tumors before the age of 30, gastrinomas or multiple islet cell tumors, and FIHP are also classified as atypical MEN1 cases." (PMID 29036195, 2017). "Many centers approach MEN1-related gastrinomas with a non-surgical management approach unless lesions reach 2 cm or larger, with disease-related survival improved with surgery in this population." (PMID 39941746, 2025). "Third, in addition to the NF-pNET in MEN1 patients, 20–71% of MEN1 patients have ZES/MEN1, which is primarily due to the presence of duodenal gastrinomas (85–95%) which are invariable multiple, small (<0.5 cm), and frequently metastasize to adjacent lymph nodes (40–60%)." (PMID 41463062, 2025). "FSG levels are elevated in almost all patients with ZES (>99%), except in some rare circumstances, such as post-parathyroidectomy in MEN1/ZES or post-noncurative gastrinoma resection." (PMID 41463062, 2025). "Similarly to initial assessment of the gastrinoma, all guidelines recommend an initial conventional imaging study (CT, MRI) to assess the possible presence and size of NF-pNET in the ZES/MEN1 patient." (PMID 41463062, 2025). "Unlike MEN1, the frequency of gastrinomas and nonfunctional pancreatic NETs, estimated to be in 25% of MEN4 cases, is significantly lower than MEN1." (PMID 37761922, 2023). "Conversely, surgical treatment does offer the only potential for cure as achieved in 75% of our MEN1 patients with gastrinomas without any post-operative mortality." (PMID 36473964, 2023). "An International Consensus Statement (ICS) from the EU also does not recommend resection of gastrinomas as an initial therapy for MEN1 patients." (PMID 36473964, 2023). "Gastric carcinoma in patients with gastrinoma has, on the other hand, rarely been described, whereas ECL cell NETs occur often in patients with gastrinoma, whether being secondary to MEN1 or of the spontaneous type." (PMID 37686307, 2023). "We have been able to perform curative surgery for gastrinomas in 75% of MEN1 patients without a post-operative death." (PMID 36473964, 2023). "Our approach for gastrinomas in MEN1 patients without evidence of hepatic metastases for over 30 years has been to perform resection." (PMID 36473964, 2023). "While surgical resection is systematically indicated in patients with functional pNET and NF-pNET ≥2 cm, a surveillance strategy is recommended in patients with small NF-pNET or small non-metastatic MEN1 gastrinoma." (PMID 32947997, 2020).
gastrinomas (continued). "Five and 10‐year OS rates for patients with MEN1 having FSG measurements not indicative for a gastrinoma were 93% and 87%, respectively." (PMID 31401809, 2019). "In one study that included 110 patients with gastrinoma, including 48 individuals with MEN1 and 62 without MEN1, the presence angiofibromas or collagenomas (single or multiple), had a sensitivity of 50–65% for MEN1 and a specificity of 92–100%." (PMID 31263451, 2019). "Because of the excellent prognosis of MEN1/ZES patients with small gastrinomas (<1.5–2 cm), these more aggressive resections are not recommended routinely in most current guidelines." (PMID 31623145, 2019). "On the basis of these considerations, as MEN1 patients can exhibit gastrinoma metastases with lack of clear-cut markers for tumor progression, some Authors have proposed earlier and more radical surgery." (PMID 24213321, 2012). "However, in many cases of ZES/MEN1 this imaged lesion at surgery is not found to be the primary gastrinoma, which are more often, small; duodenal NETs are not seen on imaging, but are in fact metastatic gastrinomas in a lymph node, or a NF-pNET." (PMID 41463062, 2025). "The most controversial point in MEN1/ZES patients is the role of surgery directed against the gastrinoma which will not be discussed in this paper dealing with medical controversies but instead dealt with in a later paper on controversies in surgical ZES issues." (PMID 41463062, 2025). "Most gastrinomas in patients with MEN1 are located in the duodenum rather than the pancreas." (PMID 37867522, 2023). "However, if MEN1 patients with gastrinomas are not treated by surgical resection, they must take PPIs for the rest of their life." (PMID 36473964, 2023). "One study assessing survival in MEN1-related gastrinoma reported the same size of a pancreatic tumor as a negative prognostic factor, although in MEN1, mostly disseminated duodenal tumors are responsible for gastrinoma and the measured PNET is probably additional NFpNET." (PMID 34122352, 2021). "This is important as it suggests that hyperplastic cells, though they harbor MEN1 germline mutations, are not yet committed to neoplastic transformation and indeed, LOH on chromosome 11q13 is a crucial event in the etiopathogenesis of duodenal gastrinomas." (PMID 33922305, 2021). "Ten‐year OS rates were 65% vs 81% for age and gender matched MEN1 patients without gastrinomas." (PMID 31401809, 2019). "Moreover, MEN1 related gastric carcinoids (types II and IV), secondary to chronic hypergastrinism, are described in up to 37% of MEN1 cases, independent of the size of the gastrinomas." (PMID 24213321, 2012). "Interestingly, while no reproducible variant has been identified in MEN1, two large kindreds followed over 30 years demonstrated a frequent prolactinoma and less frequent gastrinoma than typical MEN1 that was reproducible among kindreds and could not be explained by genetic mutation." (PMID 33716975, 2021). "MEN1/ZES patients are rarely cured because >85–100% have multiple, small duodenal gastrinomas, which metastasize to lymph nodes early, and without aggressive resections such as a Whipple procedure, are not cured by simple tumor resection or tumor enucleation." (PMID 31623145, 2019). "This may be particularly true in MEN1 patients suspected of having ZES while taking a PPI, because these patients develop numerous neuroendocrine tumors in numerous locations, which can be positive on SRI, but which are not gastrinomas." (PMID 41463062, 2025).